IL9 (interleukin 9)
Diseases named in the same sentence as IL9 in open-access papers (continued):
Sharing a sentence is not in itself a finding about the gene and the disease.
inflammatory skin disease (3 papers, 2012 to 2023). Inflammatory skin disorders covers a broad category that includes many conditions ranging in severity, from mild itching to grave medical health complications These disorders are common in people of all ages and races. "The present results is the first indication that interactions between IL-9 and mast cells may be important in inflammatory skin diseases where there is increased angiogenesis, such as AD." (PMID 22413008, 2012). "IL-9 could be involved in the pathogenesis of inflammatory skin disorders, such as AD, characterized by chronic skin inflammation that also involves mast cells." (PMID 22413008, 2012). "The relevance of ApoE, DKK1, IL12B, IL9, MANF, and VEGFC in specific inflammatory skin diseases was identified in several previous studies, as discussed further." (PMID 35393522, 2022).
interstitial lung disease (3 papers, 2017 to 2025). A diverse group of lung diseases that affect the lung parenchyma. "Thus, we can speculate that, at diagnosis, the histologic marker of lymphoid aggregates (LA), together with increased levels of tissue IL9 may help clinicians to better personalize pharmacological treatment and short-term surveillance for patients with fibrosing interstitial lung diseases." (PMID 40612945, 2025).
intestinal parasite infection (3 papers, 2013 to 2015). "Studies using IL-9 transgenic (IL-9Tg) mice have emphasized the importance of this cytokine in the control of certain intestinal parasitic infections." (PMID 24586147, 2014). "Moreover, IL-4 has been shown to control intestinal parasitic infections in an IL-5/IL-9/IL-13 triple-knockout mouse." (PMID 24586147, 2014). "Studies in human have also shown that IL-9 expression increased markedly in response to allergen challenge and IL-9 is highly expressed and localized to tissue lymphocytes during intestinal parasite infection and to CD3+ cells in bronchial submucosa and BAL." (PMID 24032029, 2013).
kidney inflammation (3 papers, 2020 to 2022). "This suggests that kidney inflammation impacts the protective effect of IL-9 on podocyte function." (PMID 35445345, 2022). "Accordingly, our findings shed light on novel and anti-inflammatory properties of IL-9 that confer preservation of kidney function and structure in kidney inflammation and may counteract kidney disease procession." (PMID 32194547, 2020). "Although IL-9 producing Treg cells have been described in inflammatory conditions such as nephritis, they have not been observed in cancer tissue so far." (PMID 35514957, 2022).
laryngeal squamous cell carcinoma (3 papers, 2021 to 2024). A squamous cell carcinoma that arises from the larynx. "The rs2069885 polymorphism was also examined in an extended haplotype analysis of the IL9 gene in patients with laryngeal squamous cell carcinoma (LSCC)." (PMID 36361964, 2022).
leishmaniasis (3 papers, 2020 to 2024). Infectious disease that is transmitted through the bite of hematophagous female phlebotomine sand flies. "Preliminary research indicated that mice receiving the anti-IL-9 vaccination demonstrated resistance to Leishmania infection, effectively preventing leishmaniasis and delaying disease progression." (PMID 39199394, 2024). "In our studies, nucleotides and AHCC showed the ability to decrease the levels of both IL-6 and IL-9 in infected macrophage/lymphocyte cocultures, which would benefit leishmaniasis patients." (PMID 32867338, 2020).
leprosy (3 papers, 2022 to 2025). Leprosy is a chronic infectious disease affecting primarily the skin and peripheral nervous system. "Previous immunohistochemical analysis of lesions from patients with leprosy showed that IL-9 was more expressed in lesions of tuberculoid leprosy compared with lepromatous leprosy." (PMID 40109344, 2025). "Another point that can help in understanding the role of IL-10 and IL-13 PB and MB leprosy and corroborate with our data, concerns the analysis of IL-9 levels in leprosy patients in this study." (PMID 38381878, 2024). "In fact, the role of Th9 lymphocytes in leprosy was evaluated in a study that demonstrated higher levels of IL-9 in the tuberculoid pole, explained by the antagonistic function of IL-9 in relation to IL-4 and IL-10, changing the immune response from the Th2 to the Th1 pole." (PMID 35379512, 2022). "In the case of leprosy, we believe that the mediators CXCL8, CCL3, CXCL10, IL-9, IL-6, and IFN-γ could be considered as potential biomarkers for the future development of rapid assays that could assist in the diagnosis and prognosis of leprosy and leprosy reactions." (PMID 40109344, 2025).
liver disease (3 papers, 2017 to 2021). "Our results underline the potential use of Th9/IL9 based immunotherapy as a promising approach for treating HCV-related liver diseases." (PMID 29937515, 2018).
lung adenocarcinoma (3 papers, 2017 to 2024). A carcinoma that arises from the lung and is characterized by the presence of malignant glandular epithelial cells. "In two murine experimental models of NSCLC, and in vitro, IL-9 prevented cell death and controlled growth of lung adenocarcinoma cells." (PMID 35514957, 2022). "Mechanistic studies in a murine model of lung adenocarcinoma highlighted the functional relevance of IL-9 signaling for cancer growth in vivo." (PMID 35514957, 2022). "Furthermore, IL-9 treatment prevented the induction of tumor cell death in lung adenocarcinoma cells indicating a pro-tumoral role of IL-9 signaling." (PMID 35514957, 2022). "Moreover, our findings demonstrate that anti-IL-9 antibodies markedly suppress tumor growth in vivo and identify IL-9R+ TILs and lung adenocarcinoma cells as targets for IL-9 signaling." (PMID 35514957, 2022). "The expression of IL-9R on lung adenocarcinoma cells may permit direct effects of IL-9 on tumor cell proliferation or apoptosis." (PMID 35514957, 2022). "In summary, subsets of tumor infiltrating lymphocytes in the lung as well as lung adenocarcinoma cells express IL9R and may thus be targets for immunomodulatory and cancer promoting effects of IL-9." (PMID 35514957, 2022).
periapical granuloma (3 papers, 2015 to 2016). Chronic nonsuppurative inflammation of periapical tissue resulting from irritation following pulp disease or endodontic treatment. "On estimation of IL-21 levels in periapical granulomas, it was demonstrated that IL-21 along with IL-17A, TNF-α (tumour necrosis factor-α), and IFN-γ were higher in active periapical granulomas, while IL-4, IL-9, IL-10, and IL-22 were higher in inactive periapical granulomas." (PMID 26998377, 2016). "The functional role of EBER in periapical granulomas is unclear; however, it has been demonstrated that EBER induces transcription of cytokines, including IL-10, insulin-like growth factor-1, and IL-9." (PMID 25884725, 2015).
prostate carcinoma (3 papers, 2021 to 2023). A carcinoma that arises from epithelial cells of the prostate gland. "Our finding is consistent with a previously reported correlation of IL-9 concentration with worsening fatigue in men with prostate cancer after radiation and chronic fatigue in patients with non-Hodgkin’s lymphoma." (PMID 34429399, 2021). "For example, IL9 was recently assigned as an essential gene in tumor immunity, and AK6 was already regarded as a biomarker in prostate cancer treatments." (PMID 36376815, 2022).
silicosis (3 papers, 2023 to 2025). Silicosis is a respiratory disease caused by breathing in (inhaling) silica dust. "Our data support that some cytokines (IL-4, IL-13 and IL-9) associated with a TH2 response are increased in the plasma of patients with silicosis, while cytokines associated with the TH1 response are practically not altered." (PMID 36675056, 2023). "Furthermore, IL-9 is highly associated with respiratory diseases, and it has been suggested that the loss or alteration of the IFN-γ signaling pathway could be related to respiratory dysfunction and the development of fibrosis in silicosis." (PMID 41008784, 2025).
uveitis (3 papers, 2012 to 2024). An inflammatory process affecting a part of or the entire uvea. "IL-9 has been shown to enhance proliferation and IFN-γ production by an IRBP specific T cell line and analysis of aqueous humor from uveitis patients reveals an increased IL-9 mRNA and protein level." (PMID 23119059, 2012). "This knowledge is necessary before a role of IL-9 in the treatment of uveitis can be envisaged." (PMID 23119059, 2012). "Until now only few groups have addressed the role of IL-9 in the pathogenesis of uveitis." (PMID 23119059, 2012). "Moreover, expression of IL-5, IL-9, IL-10, IL-13, and PDGF-AA, were significantly increased in the OT group alone, compared with the non-OT uveitis and control groups." (PMID 35646978, 2022).
acute liver failure (2 papers, 2019 to 2022). Rapid deterioration of liver function causing encephalopathy and coagulopathy. "CCL11 (Eotaxin) was selectively increased in biliary atresia patients, while IL-3, IL-6, CXCL8 (IL-8), IL-9, IL-16, MIF, CCL4 (MIP-1 β), and CXCL1 (GRO-α), were increased in both biliary atresia and acute liver failure." (PMID 30740106, 2019).
allergic conjunctivitis (2 papers, 2023 to 2024). "Epithelial cells of the ocular surface can participate in the pathogenesis of allergic conjunctivitis because of the expression of receptors for cytokines such as IL-9 and IL-33." (PMID 38541674, 2024). "Thus, the IL-9/IL-9R pathway contributes to the inflammatory process in allergic conjunctivitis." (PMID 38541674, 2024).
atopic asthma (2 papers, 2007 to 2024). An asthma that is characterized by symptoms that are triggered by an allergic reaction caused by inhaled allergens such as dust mite allergen, pet dander, pollen and mold. "Consistent with MR results, another observational study noted segmental allergen excitation in patients with atopic asthma led to increased expression of IL-9 in lymphocytes in bronchoalveolar lavage fluid." (PMID 39175819, 2024).
atrial fibrillation (2 papers, 2018 to 2024). A disorder characterized by an electrocardiographic finding of a supraventricular arrhythmia characterized by the replacement of consistent P waves by rapid oscillations or fibrillatory waves that vary in size, shape and timing and are accompanied by an irregular ventricular response. "Furthermore, increased levels of CCL5, IL-1β, TNF-α, IFN-γ, IL-9, G-CSF, and GM-CSF were observed only in the atrial fibrillation patient, when compared to other Zika patients." (PMID 29370812, 2018). "Elevated levels of CXCL8, CCL11, CCL2, CXCL10, IL-1β, IL-6, TNF-α, IFN-γ, IL-17, IL-1Ra, IL-4, IL-9, FGF-basic, PDGF, G-CSF, and GM-CSF were observed in the Atrial fibrillation patient, in contrast to uninfected controls." (PMID 29370812, 2018).
autism (2 papers, 2019 to 2021). Persistent deficits in social interaction and communication and interaction as well as a markedly restricted repertoire of activity and interest as well as repetitive patterns of behavior. "We investigated the influence of 5-AIQ-treatment in BTBR T+ Itpr3tf/J (BTBR) mice as an autism model and used flow cytometry to assess the effect of 5-AIQ on FOXP3, Helios, GATA3, IL-9, IL-10 and IL-17A production by CXCR6+ and CD4+ T cells in the spleen." (PMID 33671196, 2021).
autoimmune encephalitis (2 papers, 2012 to 2020). Inflammation of the brain secondary to an immune response triggered by the body itself. "IL9 receptors are present on astrocytes, oligodendrocytes and microglia, and IL9 dysregulation has been reported in CNS pathologies such as autoimmune encephalitis, oligodendrocyte progenitor cell proliferation and differentiation." (PMID 32225060, 2020).
autoimmune thyroid disease (2 papers, 2024 to 2025). Inflammatory disease of the thyroid gland due to autoimmune responses leading to lymphocytic infiltration of the gland. "Nevertheless, within the context of autoimmune thyroid diseases (AITDs), the effect of IL-9 on Th17 cell differentiation remains obscure and necessitates further investigation." (PMID 38605942, 2024). "Although recently published studies have demonstrated an increase in Th9 cells and IL-9 in newly diagnosed GD patients and iodine-induced autoimmune thyroiditis model, but the role of Th9 cells in refractory GD and HT patients is still unclear." (PMID 38605942, 2024). "Some studies have also reported elevated IL-9 in iodine-induced autoimmune thyroiditis models." (PMID 40895623, 2025).
bacteremia (2 papers, 2010 to 2022). "Compared with controls, the levels of IL-6, IL-8, IL-9, IL-15, IL-17, IP-10 and TNFα were significantly elevated in the bacterial sepsis-ARDS group." (PMID 21062445, 2010). "In the bacterial sepsis-ARDS group, levels of IL-6, IL-8, IL-9, IL-15, IL-17, IP-10 and TNFα are also increased versus the control group." (PMID 21062445, 2010).
chronic asthma (2 papers, 2011 to 2013). An asthma that is characterized by the development of persistent airway inflammation and recurrent attacks of breathlessness and wheezing, which vary in severity and frequency. "Therefore, the newly described association of IL-9 in the process of airway remodeling in chronic asthma highlights the need for in vivo experiments." (PMID 21765905, 2011). "Studies in IL-9 deficient mice have demonstrated that TH2 differentiation, eosinophilic inflammation, AHR, mucus and IgE production occurred normally; IL-9 is mainly required for mast cell function and airway remodeling in chronic asthma." (PMID 23940740, 2013).
chronic kidney disease (2 papers, 2023 to 2024). Impairment of the renal function secondary to chronic kidney damage persisting for three or more months. "IL-9, a key cytokine in the TH9 immune reaction, contributes to the progression of chronic kidney disease (CKD)." (PMID 39170360, 2024).
cutaneous T cell lymphoma (2 papers, 2023 to 2024). "In mycosis fungoides, the most common form of cutaneous T-cell lymphoma, malignant and reactive T cells produce IL-9 in skin lesions and the number of producing cells decreased following a successful therapy." (PMID 37398641, 2023).
dermatitis (2 papers, 2018 to 2019). An inflammatory process affecting the skin. "IL-9 and Th9 cells were found to be associated with skin inflammation." (PMID 29867972, 2018). "IL-9 plays an indispensable role in inducing and promoting atopic diseases such as dermatitis and allergic asthma." (PMID 29867972, 2018). "Emerging literature is suggesting that IL-9 potentially contributes to different types of skin disorders such as atopic dermatitis, allergic contact dermatitis, allergen-induced delayed type hypersensitivity, psoriasis, and cutaneous T cell lymphoma." (PMID 29867972, 2018). "Moreover, the development of specific dermatitis could be analyzed by monitoring the changes of IL-9 and PU.1 gene levels, suggesting that Th9 cells not only participate in the development of allergic diseases, but may also be a new target for clinical monitoring of related clinical diseases." (PMID 31414895, 2019).
epithelial ovarian cancer (2 papers, 2024 to 2025). "Th9 lymphocytes, which secrete interleukin 9 (IL-9), potentially benefit from counteracting EMT in ovarian cancer." (PMID 40362280, 2025).
Giardia infection (2 papers, 2017 to 2021). "First we studied cytokines that earlier have been shown to be up-regulated during Giardia infections in mice, i.e. IL-1, IL-2, IL-4, IL-5, IL-9, IL-10, IL-12, IL-17a, IL-17c, IFN-γ, TGF-β, and TNF-α." (PMID 34335577, 2021). "Rather, prior Giardia infection resulted ingreater IL-4 and IL-13 and increased IL-9, a potential marker of mast cell activity." (PMID 28750066, 2017).
glaucoma (2 papers, 2012 to 2024). Increased pressure in the eyeball due to obstruction of the outflow of aqueous humor. "Furthermore, individuals diagnosed with glaucoma have been observed to exhibit elevated levels of various inflammatory cytokines, including IL-9, IL-10, IL-12, IFN-α, and MIG." (PMID 38327497, 2024). "Aqueous obtained from the glaucoma patients showed increased concentration of interleukin (IL)-9 (p=0.032), IL-12 (p=0.003), interferon (IFN)-α (p=0.034), IFN-γ (p=0.002), monokine induced by interferon-gamma (MIG or CXCL9) (p=0.006), and IL-10 (p=0.050), compared to the cataract group." (PMID 22355254, 2012). "A total of 6 cytokines were found significantly elevated in glaucoma samples compared to controls, which include IL-10, IL-12, IFN-γ, IFN-α, IL-9, and CXCL-9." (PMID 22355254, 2012). "Among these cytokines, the median concentrations of IL-10 (p=0.050), IL-12 (p=0.003), IFN-γ (p=0.002), IFN-α (p=0.034), IL-9 (p=0.032), and CXCL9 (p=0.006) were also significantly higher in the glaucoma group." (PMID 22355254, 2012).
glioma (2 papers, 2017 to 2020). A benign or malignant brain and spinal cord tumor that arises from glial cells (astrocytes, oligodendrocytes, ependymal cells). "Our data emphasize the importance of Th9 cell's antitumor ability by showing that the administration of anti-IL-9 antibody abolished the glioma inhibitory ability of Th9 cells." (PMID 28002799, 2017). "The results suggest that the Ag/SEB immunotherapy induces IL-9 production in the glioma-bearing mice." (PMID 28002799, 2017). "The data show that, upon exposure to specific antigens, the glioma specific Th9 cells release IL-9 to induce glioma cell apoptosis." (PMID 28002799, 2017). "The data show that glioma specific CD4+ IL-9+ T cells were induced in glioma-bearing mice after treating with SEB and glioma extracts, but not in those treated with either SEB alone or glioma extracts alone." (PMID 28002799, 2017). "Considering the successes in immune modulation for treating cancers, TET1 is a potential marker for predicting whether the gliomas would be responsive to biological agents that target Il-9 and VTCN1." (PMID 32483272, 2020). "To test this, we treated the glioma-bearing mice with anti-IL-9 Ab together with Ag/SEB." (PMID 28002799, 2017). "In addition, IL-9+ CD4+ T cells were observed in the glioma tissue, which were more in mice treated with Ag/SEB, or SEB, or cAg/SEB than those treated with saline or Ag alone." (PMID 28002799, 2017). "The Th9 cells produce IL-9 to induce glioma cell apoptosis and inhibit the tumor growth." (PMID 28002799, 2017). "Together with glioma extracts (the specific Ag), SEB facilitates the generation of glioma specific CD4+ IL-9+ T cells." (PMID 28002799, 2017). "Although Th17 cells also produce IL-9, our data show that the SEB/glioma extract-induced IL-9+ T cells are not Th17 cells, supporting the notion of the multiple sources of IL-9." (PMID 28002799, 2017). "As shown by flow cytometry assay, the glioma-specific Th9 cells, but not the naïve CD4+ T cells, markedly induced GL261 cell apoptosis; the apoptosis was abolished by the presence of anti-IL-9 antibody." (PMID 28002799, 2017).
gouty arthritis (2 papers, 2019 to 2020). "Nonetheless, we found higher plasma levels of IL-1β, IL-1ra, IL-4, IL-6, IL-8, IL-9, IL-13, IL-17, FGF-basic, IFNγ, and TNFα in acute gouty arthritis patients." (PMID 31739430, 2019).
Hookworm Infection (2 papers, 2012 to 2026). "Moreover, hookworm infection and subsequent treatment reshape the immune landscape, highlighting the contribution of Tfh- and Th17-associated pathways, as well as IL-9 and IL-10 production, in modulating host-parasite interactions." (PMID 41823215, 2026). "Levels of mRNA encoded by the Th2/Th9 genes IL-4, IL-5, IL-13, IL-9 and GATA-3 appeared unaffected by hookworm infection using this technique." (PMID 22346753, 2012). "Our results show that experimental hookworm infection leads to a strong systemic and mucosal Th2 (IL-4, IL-5, IL-9 and IL-13) and regulatory (IL-10 and TGF-β) response, with some evidence of a Th1 (IFN-γ and IL-2) response." (PMID 22346753, 2012).
immune thrombocytopenia (2 papers, 2022 to 2024). "Furthermore, an augmented presence of Th9 cells and elevated plasma IL-9 levels in patients with active immune thrombocytopenia exhibited positive correlations with Th17 cells and IL-17 levels, respectively." (PMID 38605942, 2024).